TLR3 (toll like receptor 3)
Description:
Key component of innate and adaptive immunity. TLRs (Toll-like receptors) control host immune response against pathogens through recognition of molecular patterns specific to microorganisms. TLR3 is a nucleotide-sensing TLR which is activated by double-stranded RNA, a sign of viral infection. Acts via the adapter TRIF/TICAM1, leading to NF-kappa-B activation, IRF3 nuclear translocation, cytokine secretion and the inflammatory response.
Synonyms: CD283; IIAE2; IMD83
Tractability: Small molecule: a high-quality ligand is known; it belongs to a druggable protein family. Antibody: its Gene Ontology location is reachable by antibodies, with high confidence; UniProt places it where antibodies can reach, with medium confidence; UniProt predicts a signal peptide or a membrane-spanning region. PROTAC: UniProt records ubiquitination sites on it; a small molecule that binds it is known. Other modalities: a drug acting on it is in phase 2 or 3 trials.
Target class: Toll-like and Il-1 receptors; Membrane receptor
Safety:
Unwanted effects reported when the protein is acted on. In parentheses: how it was acted on, where the effect was seen, and who reports it.
Aspirin-Exacerbated Respiratory Disease (source: ClinPGx)
Gene: Protein-coding gene on chromosome 4 (186,068,911 to 186,088,073, forward strand). Ensembl gene ENSG00000164342.
Subcellular location: Endoplasmic reticulum membrane; Endosome membrane; Early endosome
Pathways (Reactome):
Immune System: RIP-mediated NFkB activation via ZBP1; Regulation of TBK1, IKKε-mediated activation of IRF3, IRF7 upon TLR3 ligation; TICAM1, RIP1-mediated IKK complex recruitment; TICAM1,TRAF6-dependent induction of TAK1 complex; TICAM1-dependent activation of IRF3/IRF7; TLR3-mediated TICAM1-dependent programmed cell death; Toll Like Receptor 3 (TLR3) Cascade; Trafficking and processing of endosomal TLR
Disease: RSV-host interactions; TICAM1 deficiency - HSE; TLR3 deficiency - HSE; TRAF3 deficiency - HSE; UNC93B1 deficiency - HSE
Gene Ontology:
Molecular function: double-stranded RNA binding; identical protein binding; pattern recognition receptor activity; protein binding; transmembrane signaling receptor activity; signaling receptor activity; ubiquitin-like protein ligase binding
Biological process: cellular response to mechanical stimulus; defense response to virus; extrinsic apoptotic signaling pathway; inflammatory response to wounding; necroptotic signaling pathway; positive regulation of canonical NF-kappaB signal transduction; positive regulation of chemokine production; positive regulation of gene expression; positive regulation of inflammatory response; positive regulation of interferon-alpha production; positive regulation of interferon-beta production; positive regulation of interleukin-6 production; positive regulation of interleukin-8 production; positive regulation of JNK cascade; positive regulation of type II interferon production; response to exogenous dsRNA; toll-like receptor 3 signaling pathway; toll-like receptor signaling pathway; activation of NF-kappaB-inducing kinase activity; defense response to bacterium; detection of virus; hyperosmotic response; innate immune response; negative regulation of osteoclast differentiation; positive regulation of interleukin-12 production; and 11 more
Cellular component: cell surface; cytoplasm; early endosome; lysosomal membrane; plasma membrane; endolysosome membrane; endoplasmic reticulum membrane; endosome membrane; Golgi membrane; membrane
Genetic constraint (gnomAD): Loss-of-function variants: 42 observed, 68.25 expected, observed/expected ratio (o/e) 0.62, 90% interval 0.48 to 0.8. The upper end of that interval is the gene's LOEUF score, 0.8, which puts it in group 3 of 6, group 1 being the genes least tolerant of losing a copy. Missense variants: 973 observed, 1,094.4 expected, observed/expected ratio (o/e) 0.89, 90% interval 0.84 to 0.94. Synonymous variants: 397 observed, 420.29 expected, observed/expected ratio (o/e) 0.94, 90% interval 0.87 to 1.03.
Homologues: Orthologues: chimpanzee TLR3 (99% identical), macaque TLR3 (96% identical), dog TLR3 (84% identical), pig TLR3 (84% identical), guinea pig TLR3 (83% identical), rat Tlr3 (80% identical), rabbit TLR3 (80% identical), mouse Tlr3 (79% identical), zebrafish lrrc15 (14% identical). Paralogues in human: TLR8 (24% identical), TLR7 (23% identical), TLR5 (22% identical), TLR6 (19% identical), TLR1 (19% identical), TLR10 (18% identical), IGFALS (18% identical), TLR4 (18% identical), LRRC32 (17% identical), TLR2 (16% identical), NRROS (16% identical), CD180 (16% identical), and 10 more.
Diseases named in the same sentence as TLR3 in open-access papers:
TLR3 is named in the same sentence as 480 diseases in open-access papers, as found by Europe PMC text mining. Sharing a sentence is not in itself a finding about the gene and the disease. The quoted sentences say what the papers report.
viral infection (557 papers, 2005 to 2026). "These contradictory studies on the role of TLR3 rs3775291 C/T genetic variation in susceptibility to viral infection show that the mechanism by which TLR3 rs3775291 C/T affects susceptibility/resistance to viral infections is not yet fully understood." (PMID 40831704, 2025). "When compared to their TLR3-deficient counterparts upon viral infection, WT mice showed an increase in inflammatory markers, increased local viral load, and reduced survival." (PMID 39988665, 2025). "Some studies have found an association between the TLR3 rs5743305 T/A polymorphism and viral infections." (PMID 40831704, 2025). "Once recognized by TLR3, a crucial receptor in viral infection, poly I:C triggers immune responses akin to those caused by dsRNA viruses." (PMID 40842957, 2025). "Genetic polymorphisms such as single nucleotide polymorphisms (SNPs) in the TLR3 gene are significant factors in susceptibility to viral infections like HBV and can impact the clinical outcomes of infected individuals." (PMID 40299876, 2025). "The TLR3 rs3775291 C/T polymorphism has been studied in relation to different viral infections, such as HIV-1, cytomegalovirus, tick-borne encephalitis and hepatitis B virus (HBV)." (PMID 40831704, 2025). "Among the TLRs, TLR3 has been implicated in the defense against viral infections, including human papillomavirus (HPV), the primary etiological agent of cervical cancer." (PMID 40847033, 2025). "The TLR3 rs5743305 T/A polymorphism has been studied in relation to various viral infections, including HBV, hepatitis C virus (HCV), and tick-borne encephalitis." (PMID 40831704, 2025). "TLR3 plays a critical role in the innate immune response by recognizing and responding to dsRNA, a common hallmark of viral infections." (PMID 39988665, 2025). "Poly (I : C), a synthetic double-stranded RNA (dsRNA) analog, is a molecular pattern associated with viral infection, Poly (I : C) can recognized by TLR3 and acts as the TLR3 agonist in TLR3 positive expression cells." (PMID 38550755, 2024). "TLR3 is unique in its ability to recognize double-stranded RNA, a molecular pattern associated with viral infection." (PMID 38732254, 2024). "This infection leads to increased expression of various genes associated with viral infection, including IL-6 and TLR3." (PMID 38229040, 2024). "As concerns viral infection, mast cell number increases during pulmonary viral infections in humans, and toll-like receptor 3 expression by human mast cells is implicated in the production of interferon-alpha in response to viral exposure." (PMID 38239615, 2023). "We transfected RuV-infected BeWo with poly (I:C) as a known trigger for the TLR3-associated innate immune response also active during viral infections." (PMID 37175600, 2023). "Though TLR3 is associated with double-stranded RNA (dsRNA) from viral infections, a recent study has shown TLR3 activation results in increased susceptibility and mortality in K. pneumoniae-induced pneumonic mice." (PMID 37662905, 2023). "Meanwhile, TLR3 variants have been linked to auto-immune disorders, and as risk factors of viral infection and cancers." (PMID 37414800, 2023). "TLR3 is a highly conserved molecule that recognizes double‐stranded (ds) RNA associated with a viral infection and induces the activity of the interferon response and pro‐inflammatory molecules in myeloid cells." (PMID 36840360, 2023). "Poly IC, a synthetic mimetic of viral dsRNA, is recognized by TLR3 and induces the characteristic inflammatory responses associated with a viral infection, such as production of mucus and inflammatory cytokines." (PMID 36673407, 2023). "Despite not being directly studied in relation to neurodegenerative disease, TLR3, known to recognise double-stranded RNA associated with viral infection, was downregulated in the current study." (PMID 35639336, 2023).
viral infection (continued). "The SNP of the TLR3 gene, rs3775291, which is related to viral infections, has been linked to the protection, susceptibility, and severity of a number of diseases." (PMID 37510216, 2023). "Polyinosinic:polycytidylic acid (Poly I:C) is a synthetic immunostimulant that mimics double-stranded RNA, a molecular pattern associated with viral infections and easily recognized by TLR3 of the host innate immune system." (PMID 36386162, 2022). "Among these PRRs, Toll-like receptor 3 (TLR3) stands out because it has been implicated in both protective immunity and inflammatory tissue damage during viral infections significantly affecting lung pathology as well as host survival." (PMID 36230948, 2022). "Further, excessive TLR3 activation has been shown to increase pathology in some viral infections and it has been implicated in undesirable outcomes such as virus-induced asthma." (PMID 36498932, 2022). "Poly(I:C), a synthetic analog of viral double-stranded RNA, stimulates Toll-like receptor 3 (TLR3) and thereby induces the immune response associated with viral infections, such as the loss of epithelial integrity and production of inflammatory cytokines." (PMID 35012562, 2022). "For example, the viral infection is detected by endosomal Toll-like receptor 3&7 (TLR3, TLR7), and melanoma differentiation-associated gene 5 (MDA5) of the innate immune cells in the airways." (PMID 36578545, 2022). "The expression of TLR3 in the intestinal epithelium correlated with the different susceptibility of adult versus young mice with respect to the viral infection." (PMID 34946051, 2021). "Given its role in viral recognition and the production of IFN, individuals with deficiencies in TLR3 signaling are susceptible to certain viral infections." (PMID 34199501, 2021). "The importance of the TLR3 signaling pathway in CHIKV infection has previously been demonstrated by the observation that viral infection resulted in an increase in viral load by about 100 times in deficient TLR3 mice." (PMID 33799906, 2021). "TLR3 recognizes double-stranded RNA that is a viral infection-associated ligand and also double-stranded RNA from necrotic cells and intracellular bacteria." (PMID 34623928, 2021). "Consistent with its known role in viral recognition, TLR3 polymorphisms have been linked to susceptibility to viral infection." (PMID 34199501, 2021). "Although TLR3 signaling is crucial for the protection of the host against viral infections, dysregulated signaling has been implicated in several inflammatory disorders, autoimmune diseases, cancer, and atherosclerosis." (PMID 32325904, 2020). "The increased susceptibility and high mortality of viral infections has been noted in MyD88−/− and TLR3−/− knockout mice at the early stage of infection." (PMID 32824595, 2020). "In particular, it has been shown that IRAK-4 deficient patients can control viral infection through both TLR3 or TLR independent production of type I IFN." (PMID 32038653, 2020). "Polyinosinic:polycytidylic acid (poly(I:C)) is a synthetic analogue of double stranded RNA (dsRNA), a molecular pattern associated with viral infection that can be recognized by the PRRs TLR-3, RIG-I, and MDA5." (PMID 31412613, 2019). "On the other hand, induced pluripotent stem cells (iPSCs) obtained from TLR3-deficient patients that were differentiated into various neural populations, displayed increased susceptibility to viral infection and impaired IFN secretion." (PMID 31114761, 2019). "Lastly, using visceral fat tissue from patient with diabetes, a disease known to impair eNOS and one that is associated with increased viral infection risk, we found correlations between p38, eNOS and TLR3 expression, suggesting an in vivo relationship." (PMID 30987646, 2019). "Among the PRRs, TLR3 is implicated in sensing dsRNA structures during viral infections, including HIV." (PMID 29515574, 2018).
viral infection (continued). "Viral infection was associated with an increase in the number of samples with detectable TLR3 mRNA expression in subjects with mild persistent asthma." (PMID 30463560, 2018). "Several studies in TLR3-deficient mice have demonstrated that TLR3 participates in the generation of protective immunity against some viral infections." (PMID 28198368, 2017). "Taken together, these data suggest that EAP30 is implicated in innate immune responses to viral infections triggered through either TLR3 or RIG-I while EAP45 contributes particularly to signaling through the RIG-I pathway." (PMID 29084253, 2017). "Toll-like receptor 3 (TLR3) recognizes double-stranded RNA (dsRNA), a viral replication intermediate associated with virus infection." (PMID 28717003, 2017). "The double-stranded RNA (dsRNA) is a molecular pattern associated with viral infection and recognized by Toll-like receptor 3 (TLR3)." (PMID 27031066, 2016). "IFITM3 induction was assessed in response to the dsRNA analogue poly(I : C), a molecular pattern associated with viral infection, which is recognized by Toll-like receptor 3 and induces type I IFN in porcine and bat cells." (PMID 25614588, 2015). "This compound mimics a molecular pattern associated with viral infections and it is an agonist of the Toll-like receptor 3 (TLR3), present in the endosomes of antigen-presenting cells (APC)." (PMID 26378586, 2015). "In fact, TLR3 has been implicated in both protective immunity and inflammatory tissue damage during viral infections." (PMID 24860569, 2014). "An agonist for TLR-3 is double-stranded RNA, which is associated with viral infection and engagement of the production of Type 1 IFNs that have potent anti-viral actions." (PMID 24624130, 2014). "There are several conflicting reports on the role of TLR3 signaling pathway in neurological diseases caused by viral infection." (PMID 25188232, 2014). "Our findings indicate that the absence of SP-C is sufficient to predispose the type II cell to viral infection and stimulate TLR3 mediated inflammatory responses." (PMID 23399055, 2013). "Because viral infections, in particular RV, are the most common cause of asthma exacerbations, we examined the roles of the pattern recognition receptors TLR3 and MDA5 in the response to RV infection." (PMID 21637773, 2011). "In contrast, additional TLR3 signals by poly IC after viral infection yielded a clinical improvement and less pathogenic immune responses in the CNS." (PMID 22189096, 2011). "It is well established that infection triggers activation of the innate immunity pathways, and that type I interferon response is closely linked to viral infection via activation of TLR-3 and -7/-8 by ss- and ds-RNA respectively." (PMID 21779351, 2011). "In contrast, premature activation of TLR3 signal transduction prior to viral infection leads to pathogenesis via over-activation of the pathogenic immune response." (PMID 22189096, 2011). "TLR-3 on bladder epithelial cells not only plays an important role by protecting against viral infection through secretion of IFN-gamma but also causes apoptosis of infected liver cells and has been associated with pathogenesis of biliary atresia." (PMID 22114589, 2011). "Alterations in the structure or function of TLR3 may play a crucial role in the progression of viral infections and the potential development of symptoms associated with different clinical conditions linked to HTLV-1." (PMID 40831704, 2025). "These TLR3 variants may modify treatment outcomes and disease progression and influence the host immune response to viral infections, such as HBV." (PMID 40299876, 2025).